B2M (beta-2-microglobulin)
Diseases named in the same sentence as B2M in open-access papers (continued):
Sharing a sentence is not in itself a finding about the gene and the disease.
tumor (continued). "HLA mutations have been implicated as a mechanism of immune evasion during tumorigenesis, and B2M is considered a tumor suppressor gene." (PMID 31345234, 2019). "In contrast, all of the B2m−/− mice receiving Batf3−/− spleen DCs, which lack CD8α+ DCs, died from tumor despite the presence of other DC subsets." (PMID 30774630, 2019). "B2M levels in CSF are increased in patients with neoplasia processes, CNS infections and other CNS inflammatory process." (PMID 31063510, 2019). "In B2M‐mutant dMMR tumours, the immune response is unleashed in the presence of abnormal class I presentation, but in pMMR the immune response is less marked, possibly leading to survival of the metastatic clones." (PMID 31062389, 2019). "Interestingly, B2M mutations tended to be present at higher percentiles than most HLA mutations, suggesting that B2M mutations might occur earlier in tumor development and affect a higher proportion of tumor cells." (PMID 31345234, 2019). "Of the 43 assessable B2M‐wild‐type tumours, 79.1% (34 of 43) were deemed to show low infiltration, making the difference between the two groups non‐significant." (PMID 31062389, 2019). "With no strong associations between B2M status and these other variables, comparisons of recurrence rates between B2M‐mutant and wild‐type tumours adjusting for other variables produced near identical results to the unstratified analyses." (PMID 31062389, 2019). "The correlation between TIL B7-H3 and expression of each marker in the in situ component of EMPD tumors, measured using Kendall tau-b, showed only a weak positive correlation with B2M expression in tumor." (PMID 31692889, 2019). "Among hereditary tumours, B2M-mutant MSI CRCs (n = 13) presented with significantly higher HEV density compared with B2M-wild-type (n = 16) tumours (median 0.485 vs 0.089 counts/mm2, p = 0.0237)." (PMID 31358939, 2019). "In DFT2, both copies of B2M remain intact, and B2M expression has been detected in at least a subset of tumor cells (H. Siddle, unpublished data)." (PMID 29634948, 2018). "In the MC38 model, the significant antitumor activity of anti-PD-1 against the parental was lost in JAK1/2 and B2M KOs; in these KO sublines, CyTOF analysis revealed that anti-PD-1 therapy was unable to change tumor CD8 T-cell infiltration." (PMID 30400822, 2018). "Further xenograft transplantation experiments confirmed the in vivo induction of tumor-initiation by MSCs-derived B2M." (PMID 29615660, 2018). "In the second APM mutation patient we observed a frameshift deletion event detected in B2M at a very high frequency (80% AF) in their tumor." (PMID 30400835, 2018). "We found in vitro and in vivo that MSCs-derived B2M can enhance the tumor-initiating capability of ESCC cells." (PMID 29615660, 2018). "As such, a common escape mechanism for tumor cells from immune surveillance is by mutations in the antigen presentation machinery, most notably in the JAK/STAT/B2M pathway, which are also enriched among patients with acquired resistance to immunotherapy." (PMID 30353012, 2018). "Noteworthy, B2M expression in the tumor samples of our study showed a significant positive correlation with tumor progression." (PMID 29615660, 2018). "B2M encodes the beta chain of the major histocompatibility complex (MHC) class I molecule and is up-regulated in inflammatory and tumour cells." (PMID 30266913, 2018). "Further xenograft transplantation experiments confirmed the in vivo enhancing tumor-initiation effect induced by MSCs-derived B2M." (PMID 29615660, 2018). "All these results confirmed that B2M of MSCs is essential in promoting tumor cells acquiring stem cell-like properties." (PMID 29615660, 2018). "RPS5 in combination with RPS19 (for tumor tissues) or HNRNPH (for cell lines) showed the highest expression stability compared to other genes such as B2M and GAPDH, which are the most commonly used reference genes in many human and canine OS studies to date." (PMID 29178874, 2017).
tumor (continued). "B2M plays an essential role in supporting MHC class I molecules to present tumor specific peptides to T cells." (PMID 29299180, 2017). "We examined HLA-A/-B/-C, B2M, and PD-L1 expression on thirty-six NF1-associated tumor samples by immunohistochemistry, and correlated these with tumoral CD4+, CD8+, FOXP3+, CD56+, and CD45RO+ lymphocytic infiltrates." (PMID 29137242, 2017). "Summarized, the expression of all expressed MHC I genes, including B2M, are significantly positively correlated to the PD-L1 abundance in tumor cells." (PMID 28266500, 2017). "We examined HLA I, B2M, and PD-L1 expression on pediatric and young adult tumor samples by immunohistochemistry." (PMID 29137242, 2017). "In line with the results generated from the analysis of their expression in tumor tissue, HLA-A and B2M mRNAs were present at high levels in all MCC cell lines, irrespective of the MHC class-I membrane expression." (PMID 28536458, 2017). "The functionality of NK cells from Nlrc5−/− and CD4cre Nlrc5fl/fl mice was then assessed by testing the ability to reject B2m−/− splenocytes or MHCI-negative RMA-S tumour cells." (PMID 26861112, 2016). "In another example, the relapse tumor of pair 9 (15R) gained a frameshift indel within the B2M gene (chr15:45003781–45003782)." (PMID 25123191, 2014). "The significant correlation between tumour size and the faecal expression of B2M or CEA mRNAs supports the idea that the increase in exfoliated cells in CRC originated from tumour or surrounding tissues." (PMID 20145612, 2010). "Two genes, NCOA7 and B2M, showed a similar expression level in tumor and bronchus (0.7 and 1.6 respectively)." (PMID 17697374, 2007). "Furthermore, CAR-T cells generated by deleting TRAC or B2M using CRISPR-Cas3 maintained their antigen-specific cytotoxicity against tumor cells, while exhibiting reduced alloreactivity." (PMID 42088606, 2026). "TCR/B2M KO eliminates GvHD while enhancing the anti-tumor efficacy of CAR-T cells." (PMID 40191187, 2025). "Similarly, B2M (Beta-2-Microglobulin) is associated with worse OS and disease-specific survival (DSS) in SKCM, acting as a hazardous factor by contributing to tumor progression and immune evasion." (PMID 41574107, 2025). "Conversely, when pMHCI cross-dressing on inflammatory monocytes was abolished (B2m KO tumours) but cDC1s were present, T cells were also able to expand, which reflected the established capacity of cDC1s to restimulate CD8+ T cells through classical cross-presentation." (PMID 39604727, 2025). "B2M encodes a critical component of the major histocompatibility complex class I molecule, which is required for the presentation of tumor antigens to CD8+ T cells, and alterations in B2M have been associated with decreased B2M expression and acquired resistance to ICIs51." (PMID 40588522, 2025). "Considering these findings, we speculate that CTLs antigen recognition becomes compromised due to B2M mutation/deletion, while other immune cells such as CD4+ T lymphocytes, NK cells, and γδ T cells may continue to exert cytotoxic effects on tumor cells." (PMID 40191187, 2025). "Cluster 4 expressed elevated levels of B2m and MHC-associated genes, suggesting that the activation of a subset of AMs may have anti-tumor capacity." (PMID 41567211, 2025). "Beta-2 microglobulin represents a classic example of tumor burden rather than the underlying biological aggressiveness of the disease, which limits its prognostic accuracy in determining disease outcomes." (PMID 40973877, 2025). "TRAC/B2M/PD-1 KO significantly enhances the anti-tumor efficacy of EGFRvIII CAR T cells." (PMID 40191187, 2025). "Therefore, in-depth investigation into the role of B2M in tumor immunotherapy resistance and the development of corresponding strategies are of paramount importance." (PMID 40191187, 2025).
tumor (continued). "β2-microglobulin (B2M), a key molecule in the process of tumor antigen presentation, plays a crucial role in regulating the proper folding of MHC-I molecules and the loading of peptide segments by stabilizing the structure of MHC-I molecules on the cell surface." (PMID 41514551, 2025). "Tumor fragments 1 and 3 also showed relatively higher HLA-I expression and corresponding antigen presentation, although the relatively low expression of B2M in tumor fragment 1 may explain its lower antigen display." (PMID 40777321, 2025). "TRAC/B2M/PD-1 KO eliminates GvHD and significantly enhances the anti-tumor efficacy of CAR-T cells." (PMID 40191187, 2025). "This discordance may be explained by the significant tumor burden (Metabolic Tumor Volume26 >240; beta 2 microglobulin= 9) in this second patient, and points to the presence of a residual reservoir of tumor cells with retained TNFRSF17." (PMID 41415462, 2025). "Consequently, NLRC5 contributes to reconstituting the expression and antigen presentation of B2M/MHC-I on tumor cells to potentiate CD8+ T cell dominated anticancer immunity." (PMID 40191187, 2025). "We speculate that changes in B2M levels in tumor biopsies taken early during immunotherapy may be an early indicator of subsequent clinical response." (PMID 38455061, 2024). "β2-microglobulin (B2M) plays a physiological and pathological role in tumor cells." (PMID 38280998, 2024). "The possible mechanisms by which B2M played a role might involve signaling pathways that regulated neuronal activity and tumor cells." (PMID 38743119, 2024). "Notably, we found that patients whose tumours had impaired beta 2 microglobulin (B2M) expression responded to ICB treatment, even in the absence of antigen-presenting machinery, and the same results were reported in mice lacking the CD8 + T cell compartment." (PMID 39271762, 2024). "Additionally, they showed that recognition of B2M mutated tumors by γδ T cells was mediated by NKG2D, and checkpoint blockade further increased the number of Vδ1/3 T cells in the tumor." (PMID 38321065, 2024). "Similarly, the expression of genes related to antigen processing and presentation such as Tap1, Tap2, B2m, and Psmb9, was also upregulated in tumors from hsBCL9z96-treated CT26 tumor-bearing mice and MC38 tumor-bearing Bcl9/Bcl9l deficiency mice." (PMID 38811552, 2024). "Half of the patients had elevated beta-2-microglobulin level indicating elevated tumor burden." (PMID 39194701, 2024). "B2M and HLA-A loss was increased in metastatic lesions compared to primary tumors, indicating selection of MHC class I low clones in metastatic and refractory tumor cells." (PMID 38455061, 2024). "Interestingly, B2m–/– B16 tumor–bearing mice treated with r3LCMV showed improved tumor control relative to control-treated mice, suggesting that antigen presentation via MHC was not completely required for the antitumoral effect." (PMID 38861331, 2024). "One can speculate that the deletion of tumor B2m, LMP2, or Jak1 impacts cytokine and chemokine gradients in the TME given the altered and differential immune cell infiltration observed in these KO tumors relative to each other and to wt tumors." (PMID 38427670, 2024). "This loss of HLA-I is attributed to accumulating mutations and heterozygosity loss at the HLA-I and B2M loci, which poses a significant challenge for developing effective anti-tumor immunotherapies by rendering T cells without targets." (PMID 38256174, 2024). "In our patient, we have not confirmed the loss of expression of B2M or MHC-I expression in the tumor by immunohistochemistry due to lack of sufficient tumor material." (PMID 38280045, 2024). "Cumulatively, our results underscore that loss of B2M and HLA-A expression is specific to tumor cells but in the majority of cases it is not permanent and can be upregulated through immunotherapy treatment." (PMID 38455061, 2024). "Further, B2M plays a significant biological role in tumor development and immune regulation." (PMID 39453509, 2024).
tumor (continued). "Next, we co‐cultivated Renca cells with CD8+ T cells by a 1:3 ratio for 24 hours and found that a higher Annexin V positive proportion in the Renca cells transfected with the B2M‐Overexpression group while the remaining tumor cell numbers were lower than those in the vehicle group." (PMID 37526345, 2023). "While B2M loss did not negatively impact tumor growth either in vitro or in vivo, the anti-tumor effect of pevonedistat was fully abrogated." (PMID 37031300, 2023). "Beta-2-microglobulin imbalance may promote tumor escape from recognition by CD8+ T cells and play a role in neutrophil degranulation." (PMID 37388743, 2023). "Importantly, enhanced antitumor responses by Pikfyve-depletion were CD8+ T cell- and MHC-I-dependent, as CD8+ T cell depletion or B2m knockout rescued tumor growth." (PMID 38011559, 2023). "In B2m-null KPC tumours, the effect of AC484 depended on the presence of NK cells." (PMID 37794185, 2023). "Although rare, B2M alterations were also significantly associated with increased expression of TRDV1/TRDV3 loci in this context (two-sided linear regression, P = 2.2 × 10−17, adjusted for tumour type)." (PMID 36631610, 2023). "Notably, the expression of genes encoding MHC class I molecules, such as human leukocyte antigen (HLA)-A, HLA-B, HLA-C, and HLA-E, and beta-2 microglobulin, significantly decreased in After Tumor." (PMID 38136558, 2023). "Combining EZH2 inhibitior with ICB reduces tumor growth by changing the expression of B2M." (PMID 38041084, 2023). "Notably, γδ T cells in B2M-deficient cancers showed co-expression of CD103 and CD39, which has been reported to identify tumour-reactive CD8+ αβ T cells in a variety of cancers." (PMID 36631610, 2023). "B2M protein expression in tumor showed a strong agreement with the RNA levels of B2M expression." (PMID 37057033, 2023). "Refining the analysis for specific genes and cancer types revealed that two genes from the antigen presentation pathway (that is, B2M and CALR) displayed recurrent patterns of inactivating mutations and focal biallelic deletions across several tumor types, as well as in the pan-cancer cohorts." (PMID 37165135, 2023). "Biomarkers such as LDH or B2M correlate with tumor burden and have a prognostic role." (PMID 37445974, 2023). "The reduction of B2M in tumor cells may lead to the reduction of MHC class I, thus avoiding the immune surveillance of T cells." (PMID 37098551, 2023). "In addition, we observed an increased infiltration by immune cells, as well as higher immune checkpoint expression among B2M-high cases, predominantly in the tumor compartment." (PMID 37057033, 2023). "TAMs can shield tumor cells from phagocytosis by combining with B2M through LILRB1." (PMID 38041084, 2023). "Furthermore, human clinical paraffin‐embedded RCC tissues were also collected and immunohistochemical staining assays were performed, showing that the expression of B2M in tumor samples was much lower than that in cancer‐adjacent normal tissues." (PMID 37526345, 2023). "In contrast, the increase in HDAC2 and B2M mutants in CRC appeared to be associated with a differentiated CD4+ Th2 subpopulation, which could affect tumor promotion." (PMID 37046620, 2023). "Previous studies have suggested pre-existing CKD, raised beta-2 microglobulin (reflecting a high tumour burden), and the presence of mucositis grade 3 or 4 as independent prognostic factors for developing CKD after ASCT have been associated with increased morbidity." (PMID 35413986, 2022). "Whereas, no tumor cell lines characterized by HLA class I and B2M gene mutations leading to tumor immune escape have been established." (PMID 36611830, 2022). "The NAF1 and Beta-2 Microglobulin (B2M) expression data from CRC patients were determined from tumor and healthy intestinal tissue samples, and whether the patients were genotyped for the SNP rs17042479." (PMID 36067202, 2022).
tumor (continued). "In our study, one FL case (Case-16) had the BTG1 p.E46D and B2M p.Q22* mutations specifically in plasma cfDNA but not in the tumor tissue DNA of the same FL patient." (PMID 35795062, 2022). "Therefore, we investigated the expression level of beta-2-microglobulin mRNA (B2M) and human leukocyte antigen (HLA) in both groups of patients and found the expression of B2M is downregulated compared to the responding tumours." (PMID 36248850, 2022). "Two cases presented with mixed APM pattern switching from a positive ICI response in a tumor with normal B2M expression to lack of sensitivity towards the ICI therapy in tumors with B2M loss of function." (PMID 36615128, 2022). "Subsequently, we analyzed SQLE expression and its association with biomarkers of MHC (B2M, HLA-B, HLA-C, TAP1, and TAP2), dendritic cells (BATF3), macrophages (CD68 and IL1A), type-I anti-tumor responses (CD8A and GZMB), and cell proliferation (MKI67) in 178 PAAD tissues." (PMID 35720314, 2022). "They additionally proved that CD8+ T cells showed considerably lower cytotoxicity than B2M knockout tumor cells, indicating that B2M could mediate tumor cell escape from ICI therapy through MHC class I expression." (PMID 36119033, 2022). "This means that MHC class I levels in MHC class I-deficient tumor cells caused by the B2M gene alteration will not be restored regardless of the type of immunotherapy." (PMID 36046045, 2022). "Hence, it is important to develop techniques to detect LOH in the HLA and B2M genomic regions in DNA obtained from solid tumor tissues as well as in tumor cell lines." (PMID 34680201, 2021). "HLA-C and B2M are required to present tumor neoantigens to cytotoxic CD8+T cells." (PMID 35173763, 2021). "On the whole, while the loss of one copy of B2M is relatively common across multiple cancers, a complete loss of B2M expression is uncommon, most likely because a complete loss of MHC-I makes the tumor susceptible to NK cell-mediated killing (more details in Section 4.2.1)." (PMID 34201655, 2021). "We confirmed the loss of B2m on MC38 cell surface by flow cytometry, and then implanted B2m-deficient tumors into Cd4-Cre+Lsd1f/f mice or littermate controls to monitor tumor growth." (PMID 34819502, 2021). "It was hypothesized that this may provide a survival benefit for the B2M mutant tumours in an environment where in spite of low infiltration of Tregs, the active immune system fails to induce a response by not recognising the tumour cells." (PMID 34067951, 2021). "Although LuCaP 145.1 cells banded at the [strom] density in Percoll, no outgrowth of mouse fibroblasts that might be present in the tumor specimen was seen (as monitored by PCR with primers for mouse B2M)." (PMID 34911496, 2021). "In this study, we detected B2M mRNA levels in 33 tumor types and corresponding normal samples." (PMID 33960680, 2021). "The hypothesis of B2M-mutant tumor cells being “trapped” in the peritoneum is supported by the metastatic patterns of B2M-mutant MSI cancers observed in our study." (PMID 34168989, 2021). "Next, we explored the correlation between B2M mRNA expression and tumor grade or IDH1 phenotype." (PMID 33960680, 2021). "B2M expression was correlated with tumor grade and was downregulated in IDH1 mutant samples." (PMID 33960680, 2021). "In one case we observed a complete loss of HLA-ABC/B2M expression (sample 4), and one tumor did not have any alterations based on immunohistological analysis (sample 5)." (PMID 34298868, 2021). "B2M also suppressed anti-tumor immunity through immune related processes." (PMID 33658560, 2021). "A recent proof of principle study (carried out in colorectal cancer and melanoma pre-clinical models) has shown that loss of B2M, a genetic alteration that abrogates MHC class I expression and prevents CD8-mediated tumor recognition, can be overcome by a therapy designed to activated NK cells." (PMID 33276569, 2020).